NUP214 (nucleoporin 214)
Diseases named in the same sentence as NUP214 in open-access papers (continued):
Sharing a sentence is not in itself a finding about the gene and the disease.
cancer (23 papers, 2010 to 2026). A tumor composed of atypical neoplastic, often pleomorphic cells that invade other tissues. "T-cells specific against two mutated cancer-associated genes, NUP214 and JAK1, recognized autologous tumors." (PMID 31221207, 2019). "The biological relevance of patient-derived T-cells against neoantigens from known cancer-associated genes, NUP214 and JAK1, were confirmed by the demonstration of autologous tumor recognitions." (PMID 31221207, 2019). "Therefore, both direct presentation by cancer cells and indirect cross-presentation of tumor-derived NUP214 by hematopoietic antigen-presenting cells are possible as a mechanism for activation of mutated NUP214-specific CD4+ T-cells in the tumor microenvironment." (PMID 31221207, 2019). "Our results hence attempt to explain why miR-133b is generally downregulated in tumours and lay out the potential for Nup214 as a therapeutic target in the treatment of cancer." (PMID 25743594, 2015). "Examination of head and neck tumour tissues and cancer cell lines revealed that Nup214 and miR-133b expressions are negatively correlated." (PMID 25743594, 2015). "It is in addition involved in regulation of intracellular signaling, cell cycle progression/mitosis and programmed cell death even in cancer cells; its fundamental cellular importance is further illustrated by the observation that genomic knockout of NUP214 leads to embryonic lethality in mice." (PMID 41002427, 2025). "In the current study, we describe a case of SET::NUP214-positive malignant neoplasm in a pediatric patient presenting in a form of simultaneous occurrence of AML and PTCL and verify the common nature of cells in the BM and lymph node using several molecular techniques." (PMID 37833906, 2023). "miR-133b and NUP214 expressions were validated in cancer cell lines and tissues by Real-Time PCR." (PMID 25743594, 2015). "Hence, a systemic study of miRNAs involved in the regulation of Nup214 and its interacting partners is warranted to fully understand the impact of miRNAs on the development and progression of cancer." (PMID 25743594, 2015). "It was also found that the NUP214 expression levels are elevated in a number of cancers." (PMID 25743594, 2015). "This analysis shows that the 1CT7 specific mutated genes are altered in 30.4% of all CRC cases whereas A1309 specific mutated genes are altered in 73.6% of all CRC cases, among which five genes are known cancer genes, i.e. PBRM1, MYB, PRDM16, BCR and NUP214." (PMID 25923178, 2015). "NUP214 is an important player in nuclear export mediated by the β-karyopherin CRM1 and CRM1 inhibition in turn has been proven beneficial in clinical trials as anti-cancer strategy." (PMID 32934780, 2020). "Interestingly, in healthy cells, Nup88 relies on heterodimerization of Nup214 for its protein stability; however, Nup214 is not elevated in these malignancies, indicating that this relationship can be decoupled in cancer." (PMID 33375634, 2020).
tumor (16 papers, 2010 to 2025). "As NUP214-specific CD4+ T-cell responses was detected in the tumor from Pt #19, we reasoned that the mutated NUP214 epitope was naturally presented in the tumor microenvironment." (PMID 31221207, 2019). "All these studies provided substantial evidence of the role of NUP214 as a tumor-promoting gene and that inhibiting its expression can regulate the process of cell death." (PMID 39744516, 2025). "Based on the availability of autologous tumor specimens, we focused on NUP214 neoepitope-specific CD4+ T-cells obtained from TILs of Pt #19 and JAK1 neoepitope-specific CD4+ T-cells obtained from TILs of Pt #11." (PMID 31221207, 2019). "An example is the NUP214 mutation, which we observed in the index patient and which very likely did not increase tumor susceptibility." (PMID 24373500, 2013). "Altogether this suggests that the NUP214 mutation does not contribute to the tumor spectrum in our patient." (PMID 24373500, 2013). "miR-133b-3p targets MET (involved in invasive tumour growth), the gene encoding ferritin light chain (FTL), lncRNA LINC00467 (promoting CRC cell resistance against 5FU), a component of the nuclear pore complex proto-oncogene nucleoporin 214 (NUP214) and some others." (PMID 32610706, 2020). "Therefore, we tested whether NUP214-specific CD4+ T-cells are activated by autologous tumor cells." (PMID 31221207, 2019). "The increased expression of nucleoporins Nup153 and Nup214 and importin-beta factors strongly predicts elevated MAPK nuclear import in tumor tissues." (PMID 20174585, 2010). "Indeed, NUP214 neoepitope-specific CD4+ T-cells produced IFN-γ specifically against tumor cells, but not against autologous PBMCs." (PMID 31221207, 2019).
infection (14 papers, 2012 to 2025). The state of being infected such as from the introduction of a foreign agent such as serum, vaccine, antigenic substance or organism. "To pinpoint where viral capsid accumulates with H27, we treated cells shortly before infection and imaged CA localisation at 2 and 6 hpi using high-resolution Airyscan and co-labelling NPCs with a Nup214 antibody." (PMID 39358603, 2024). "We found no notable differences between knock-down and control cells at the time of infection, except for Nup214 KD cells which had 50% reduced viability." (PMID 23049930, 2012). "Later during infection, other Nups have been reported to be targeted as well by both 2Apro (Nup62, Nup153, and Nup358), and by 3Cpro (Nup153, Nup214, and Nup358), but the extent to which these contribute to the NCTD is unknown." (PMID 40875754, 2025). "In the case of HIV-1G89V, whose infection was inhibited by NUP88 and NUP214 depletion in HeLa cells, expression of MX2 completely restored infection." (PMID 30084827, 2018). "Notably, 9 nucleoporins (NUP58, NUP214, NUP98, NUP54, NUP62, NUP88, NUP153, POM121/NUP121 and RANBP2/NUP358) and the mRNA export factor Rae1 were present in both the CebN infection and transfection interactomes." (PMID 38712050, 2024).
hematological malignancies (7 papers, 2011 to 2025). "We reviewed the characteristics and prognostic significance of the SET-CAN/NUP214 fusion gene in hematological malignancies." (PMID 35905214, 2022). "The mechanism, clinical characteristics, therapy and prognosis of the SET-CAN/NUP214 fusion gene in hematological malignancies require further research." (PMID 35905214, 2022). "NUP98, NUP160, and NUP214 have both been reported as fusion proteins with a variety of partners that lead to hematologic malignancies and angiosarcoma." (PMID 31867128, 2018). "This early work identified fusions of NUP98 and NUP214 that led to a variety of de novo hematologic malignancies." (PMID 31867128, 2018). "SET-CAN/NUP214 fusion gene encodes a protein containing an almost complete portion of SET fused to the carboxy-terminal two-thirds of CAN, which is a rare gene rearrangement occurs primarily in hematological malignancies." (PMID 37909026, 2023). "ACACA, RARA, NOTCH1 and NUP214 are known to form translocations in various types of hematological malignancies while many other fusion genes involve suspected oncogenes, such as RPS6KB1 (RPS6KB1-TMEM49 and RPS6KB1-SNF8), GSDMB (TATDN1-GSDMB) and MCF2L (LAMP1-MCF2L)." (PMID 21247443, 2011).
blood cancer (3 papers, 2023 to 2024). "Therefore, our data reveal significant plasticity of SET::NUP214-positive hematological neoplasms, with the ability of BM malignant progenitors to diverge and differentiate in different cellular microenvironments." (PMID 37833906, 2023).
genetic disorder (1 paper, 2024). "Mutations in the NUP214 gene are known to lead to susceptibility to acute infection-induced encephalopathy type 9 (ILAE9) (Online Mendelian Inheritance in Man (OMIM), 114350, an autosomal recessive genetic disorder)." (PMID 39650934, 2024). "Homozygous or compound heterozygous mutations in the NUP214 gene have been associated with susceptibility to acute infection-induced encephalopathy type 9 (ILAE9) (Online Mendelian Inheritance in Man (OMIM), 114350), an autosomal recessive genetic disorder." (PMID 39650934, 2024).
neurodevelopmental disorder (1 paper, 2022). A behavioral and cognitive disorder with onset during the developmental period that involves impaired or aberrant development of intellectual, motor, or social functions. "Variants in the NUP214 gene cause acute febrile encephalopathy and rare mutations in ASH1L are connected to numerous neurodevelopmental disorders [reviewed in]." (PMID 36061196, 2022).
NUP214 also shares sentences with these, for which no sentence is quoted: cardiac hypertrophy (29 papers); neurodegenerative disease (8); diabetes (7); heart failure (7); T-cell acute lymphoblastic leukemia (6); Alzheimer disease (5); Hypertension (5); memory impairment (5); myelodysplastic syndrome (5); prion disease (5); B-cell acute lymphoblastic leukemia (4); dementia (4); hypertrophy (4); myocardial infarction (4); amyloid (3); chronic myeloid leukemia (3); depression (3); epilepsy (3); glaucoma (3); Hyperglycemia (3); Myocardial fibrosis (3); atrial fibrillation (2); autoimmune disease (2); cardiomyopathy (2); Cerebral ischemia (2); cognitive decline (2); head and neck tumor (2); ischemia (2); lung carcinoma (2); lymphoma (2).
A further 66 diseases each share a sentence with NUP214 in 2 papers or fewer.